S100B (S100 calcium binding protein B)
Diseases named in the same sentence as S100B in open-access papers (continued):
Sharing a sentence is not in itself a finding about the gene and the disease.
Sepsis (40 papers, 2008 to 2025). Sepsis is defined as life-threatening organ dysfunction caused by a dysregulated host response to infection. "Neutralization of S100B in a rat sepsis model increased cognitive performance scores, and pharmaceutical suppression of S100B reduced gliosis and neuronal loss." (PMID 38396891, 2024). "Utilizing multivariate Logistic Regression, an integrated nomogram was formulated, incorporating salient indicators such as CCT, S100B, and PI, thereby emerging as a robust diagnostic tool for the clinical management of sepsis." (PMID 38274881, 2023). "In summary, elevated serum S100B levels on day 3 and the dynamic changes in serum S100B levels from day 3 to 1 were closely associated with brain dysfunction and mortality in sepsis patients." (PMID 32382007, 2020). "A growing number of studies have suggested that increased serum S100B levels are associated with brain dysfunction in sepsis patients." (PMID 32382007, 2020). "Since 2010, some studies have also verified that elevated serum S100B levels are associated with sepsis brain damage." (PMID 32382007, 2020). "The main finding of this study was that the dynamic changes in serum S100B levels from day 1 to day 3 were associated with brain dysfunction and fatal prognosis in patients with sepsis." (PMID 32382007, 2020). "▪ The S100B peptide is a potential serum biomarker for bedside diagnosis and follow-up of sepsis-associated encephalopathy." (PMID 20374626, 2010). "In the future, monitoring the dynamic changes in serum S100B levels could be a better way of observing the occurrence and progression of sepsis-associated encephalopathy." (PMID 32382007, 2020). "Serum S-100β may be a more sensitive biomarker than NSE for detection of sepsis associated encephalopathy." (PMID 27089280, 2016). "Furthermore, it was observed that serum S100B was associated with prognosis in sepsis patients." (PMID 39039544, 2024). "In parallel, elevated S100β levels in sepsis patients have shown moderate correlation with SAE onset and unfavorable prognosis, reinforcing its potential as both a prognostic and diagnostic biomarker in SAE." (PMID 40714984, 2025). "Levels of S100B in the first hours of life were correlated with the adverse event of seizures, late sepsis and death, and negatively correlated with Apgar score (1 min) and acidosis (SBE, first hours of life)." (PMID 37292373, 2023). "Concerning the changes in biomarkers, one-third of our patients had abnormal levels of NSE or S100B at any time point in the first seven days of sepsis." (PMID 35739230, 2022). "Increased serum levels of S100b is reported after cardiac surgery as well as after hypoperfusion in patients with sepsis." (PMID 35429240, 2022). "Both KYNA and SZR-104 significantly reduced (the latter more effectively) the sepsis-induced increase in S100B plasma levels." (PMID 34475875, 2021). "Several studies have demonstrated that S100β, GFAP and NSE are serum markers of sepsis-associated brain diseases." (PMID 34705665, 2021). "In our model, S100B served not only as a marker of astrocyte-derived brain injury but also as an indicator of early BBB damage during sepsis." (PMID 34475875, 2021). "To date, only a few prospective studies have aimed at assessing the role of dynamic changes in S100B levels in patients with sepsis brain injury." (PMID 32382007, 2020). "The results obtained in this study support the notion that the dynamic detection of serum S100B levels is a better and more effective method to monitor brain injury in sepsis." (PMID 32382007, 2020). "An elevatedlevel of these proteins is associated with cytokine activation in sepsis.S100B, NSE, and GFAP have been used to diagnose sepsis-induced brain injury." (PMID 32779431, 2020). "We investigated the role of dynamic changes of serum levels S100B protein in brain injury and poor outcome of sepsis." (PMID 32382007, 2020).
Sepsis (continued). "The aim was to evaluate the role of S100B levels at different time points and to evaluate the dynamic changes in S100B levels on prognosis and brain injury in sepsis." (PMID 32382007, 2020). "Overall, the results of this analysis showed that the serum S100B levels on day 1 were imprecise as biomarkers of sepsis brain injury." (PMID 32382007, 2020). "In the sepsis with BoxA treatment group, however, S100β and the NSE levels were both decreased in comparison to the sepsis group (n=6, P<0.05)." (PMID 29190939, 2017). "Previous clinical studies have been focused on neuron-specific enolase and S100B to diagnose brain injury in sepsis, with heterogeneous results." (PMID 29058589, 2017). "In adults with sepsis and septic shock, both serum S-100β and GFAP were elevated compared to controls." (PMID 27089280, 2016). "In Hamed's study, children with sepsis-induced encephalopathy have elevated serum and cerebrospinal fluid levels of sICAM-1, NO, and S100B compared to those with sepsis only." (PMID 24883317, 2014). "Sepsis aggravated ongoing brain dysfunction as a component of multiple organ dysfunctions which was reflected by S100B elevation and higher organ dysfunction SOFA scores, respectively." (PMID 24883321, 2014). "In contrast with these results, we previously reported data about serum S100B measurement in 19 patients with severe sepsis excluding those with septic shock; even if the protein was increased in 56% of patients, it didn’t correlate with the presence of SAE." (PMID 23905041, 2012). "Plasma levels of S100β and NSE can predict early ICU mortality; plasma levels of S100β measured at ICU admission are independent predictors of survival in sepsis patients." (PMID 23245494, 2012). "The observed high mortality rate is also in line with our earlier findings, indicating a 70% mortality in S100B-positive patients with severe sepsis." (PMID 20374626, 2010). "We have previously shown that S100B levels in severe sepsis better reflected the presence and prognosis of low consciousness SAE than the GCS." (PMID 20374626, 2010). "As for clinical use, S100B may provide valuable information in combination with other biomarkers and clinical parameters for assessing the severity of sepsis and predicting outcomes." (PMID 39201697, 2024). "Currently, recommendations or guidelines regarding the use of S100B specifically as a sepsis biomarker may be limited." (PMID 39201697, 2024). "Compared to the “non-sepsis” group, “sepsis” patients presented a significant increase in the S100β protein concentrations at day 1 (0.94 μg/L versus 0.52 μg/L, p = 0.03), and more frequent EEG alterations (i.e., severe slowing, discontinuous background, and a lower prevalence of sleep patterns)." (PMID 37311846, 2023). "On the other hand, correlation of early S100B on day1 with late sepsis is intriguing." (PMID 37292373, 2023). "In patients with severe sepsis and septic shock, decrease in cerebral perfusion pressure correlated with increased serum S100β levels; therefore, attempts may be made to increase mean arterial pressure to mitigate brain injury." (PMID 32806705, 2020). "Therefore, we designed a prospective cohort study to measure the serum S100B levels on days 1 and 3 in sepsis patients after admission to the intensive care unit (ICU)." (PMID 32382007, 2020). "For sepsis patients with sustained brain damage, serum S100B levels may continually increase, especially in patients with severe encephalopathy." (PMID 32382007, 2020). "Our findings also call for more comprehensive experimental and clinical research to clarify the relationship between S100B protein behaviour and the extent of concomitant electrophysiological, cerebrovascular, and neurohormonal alterations in severe clinical sepsis and septic shock." (PMID 20374626, 2010). "Whether serum S100B elevation in sepsis always reflects blood-brain barrier disruption is difficult to prove." (PMID 20374626, 2010).
Sepsis (continued). "However, in a large study including 170 patients with severe sepsis and septic shock, a similar proportion of patients showed increased S-100β and NSE levels, with S-100β being a better predictor of disease severity." (PMID 18457586, 2008). "Furthermore, levels of NSE and S100B were similarly elevated in children with and without sepsis-associated encephalopathy and full neurological recovery after three months, indicating preserved CNS integrity at the cellular level." (PMID 41360904, 2025). "Specificity of SAE-related biomarkers: while biomarkers like cytokines (e.g., IL-6, TNF-α), S100B protein, and other markers of neuronal injury are elevated in both sepsis and SAE, their levels may be particularly associated with brain dysfunction in sepsis." (PMID 40529149, 2025). "Indeed, there was also an increase in s100β and miR370-3p in sepsis mouse brains that could be detected in serum and proposed as biomarkers for encephalopathy during sepsis." (PMID 35628259, 2022). "Meanwhile, S100B could not reflect all the pathological changes associated with brain injuries in sepsis." (PMID 32382007, 2020). "For instance, a sepsis patient with CCT, PI, and S100B values of 13 s, 1.3, and 0.18 μg/L, respectively, would accumulate a nomogram score of ~170, which translates to an estimated 70% likelihood of SAE development." (PMID 38274881, 2023). "Sepsis was characterized by significantly elevated ROFA scores, while the increased BBB permeability and plasma S100B levels demonstrated brain damage." (PMID 34475875, 2021). "In the present study, the expressions of S100b,Nse, and Gfap were significantly increased in CLP groupswhich indicated sepsis-induced brain injury." (PMID 32779431, 2020). "ELISA results exhibited higher levels of serum S100β and NSE in the sepsis group than those of the sham group (n=6, P<0.05)." (PMID 29190939, 2017). "From the present study, antagonism of brain HMGB1 was effective in decreasing serum S100β and NSE levels, which implicating a potential therapeutic role of targeting HMGB1 in ameliorating sepsis induced brain dysfunction." (PMID 29190939, 2017). "Moreover, S100B, a ligand of Receptor for Advanced Glycation End products (RAGE), is secreted by astrocytes in the CNS during sepsis, which is also recognized as a DAMP." (PMID 35603184, 2022). "Although an increasing number of studies have confirmed that serum S100B levels are elevated in sepsis brain damage, these studies have not been able to accurately assess sepsis brain injury within the initial 24 hours from septic onset." (PMID 32382007, 2020). "The use of Dotrecogin alpha has been suggested to reduce neuronal damage in human sepsis, even if its effect has been evaluated by measuring of serum S100B, which is not a reliable marker of SAE, like previously reported." (PMID 23905041, 2012). "Moreover, S100β levels were significantly higher in SAE patients compared to those without NE, both when samples were collected within 1 day (P < 0.001) and after 1 day (P < 0.001) of sepsis onset." (PMID 41245863, 2025). "BBB damage in patients with sepsis was observed using different strategies: (i) post-mortem; (ii) after incubating hCMEC/D3 cells, as a model of BBB, in presence of serum from septic patients; and (iii) indirectly, by measuring plasma S100B, a marker of BBB lesion." (PMID 33608025, 2021). "We previously showed that, due the short half-life time, S100B could only predict the early ICU nonsurvivors of sepsis." (PMID 24883321, 2014). "However, other studies have also shown that neuron-specific enolase (NSE) levels but not S100B levels in severe sepsis or septic shock could predict fatal outcome in patients." (PMID 32382007, 2020). "If biomarkers such as S100B or GFAP are elevated, clinicians can use these markers not only as indicators of severe sepsis but also as potential flags for brain involvement." (PMID 40529149, 2025).
Sepsis (continued). "Although the long-term cognition function was not assessed, Li and colleagues proved that inhibition of S100β/RAGE/NF-κB pathway reduced neuroinflammation, oxidative stress, and reactive gliosis in the hippocampus in the CLP sepsis model." (PMID 35603184, 2022). "Although a study reported that elevated S100B levels could not reflect the severity of brain injury during sepsis, all patients with a GCS score ≤ 8, except one patient, in their study had elevated serum S100B levels." (PMID 32382007, 2020).
epilepsy (38 papers, 2010 to 2025). A brain disorder characterized by episodes of abnormally increased neuronal discharge resulting in transient episodes of sensory or motor neurological dysfunction, or psychic dysfunction. "Tissue S100B level correlated with seizure frequency and loss of nerve cells in a rat model of epilepsy." (PMID 36766708, 2023). "The reduction of S100B not only causes the disorder of the blood-brain barrier function but also leads to the imbalance of microglia function that both will induce epilepsy." (PMID 33959658, 2021). "Most of the subgroup analyses, including those of country, assay type and publication language, demonstrated a statistically significant association between peripheral blood levels of S100B and epilepsy." (PMID 31156363, 2019). "Sensitivity analysis showed that no single study significantly influenced the overall association of peripheral blood levels of S100B and epilepsy." (PMID 31156363, 2019). "Additionally, S100β is associated with brain neuroinflammation, such as in conditions like epilepsy." (PMID 40589656, 2025). "Given the fact that BBBD and subsequent S100B appearance is serum is a hallmark of many acute or chronic neurological diseases as well as in animal model of seizures or in human epilepsy, we wished to determine the fate of circulating S100B in control or post-status epilepticus animals." (PMID 24988410, 2014). "MMP-9 and S100B, the proteins involved in blood-brain barrier integrity, are particularly interesting because they are increased in epilepsy patients in the interictal period and are triggered by the seizures themselves." (PMID 40076533, 2025). "Several clinical and experimental studies investigated S100B’s potential as a biomarker and its prognostic value in epilepsy since it indicates astroglial damage." (PMID 40904734, 2025). "MMP-9 and S100B, the proteins involved in blood-brain barrier integrity, are widely studied as biomarkers in many diseases, including epilepsy." (PMID 40076533, 2025). "In good accord, it has been reported that serum S100B levels were increased in epilepsy patients and after SE." (PMID 40904734, 2025). "Serum levels of S100β are elevated in several neurological disorders including epilepsy, traumatic brain injury and schizophrenia." (PMID 38388736, 2024). "Inherently, an anti-inflammatory drug such as metformin was shown to reduce S100B brain levels in a kainic-acid-induced model of epilepsy." (PMID 37298554, 2023). "Significant correlations between the levels of the neurospecific proteins studied herein suggest interactions between BDNF, NSE, VILIP-1, and S100B in the pathophysiology of epilepsy." (PMID 38203674, 2023). "The neurospecific proteins BDNF, NSE, VILIP-1, and S100B play an important role in the pathogenesis of neuropsychiatric disorders, including epilepsy." (PMID 38203674, 2023). "Serum levels of MMP-9, MMP-2, TIMP-1, TIMP-2 and S100B are elevated in patients with epilepsy in the interictal period, which suggests chronic processes of BBB disruption and restoration." (PMID 36766708, 2023). "The potential involvement of S100B in the etiopathology of epilepsy has been investigated in distinct animal models." (PMID 37298554, 2023). "Recently, VILIP-1 and S100B have been proposed as biomarkers with greater specificity for diagnosing epilepsy and determining the severity of the disease." (PMID 38203674, 2023). "Serum levels of MMP-9, MMP-2, TIMP-1, TIMP-2 and S100B were higher in patients with epilepsy in comparison to control group (p < 0.0001; <0.0001; 0.001; <0.0001; <0.0001, respectively)." (PMID 36766708, 2023). "There are no data on the correlation between BDNF and the neurospecific proteins NSE, VILIP-1, and S100B, which reflect brain damage in epilepsy." (PMID 38203674, 2023). "Serum levels of S100B were overall increased in patients with SE compared to both patients with epilepsy and healthy controls." (PMID 37569895, 2023).